HOXC4 (homeobox C4)
Description:
Sequence-specific transcription factor which is part of a developmental regulatory system that provides cells with specific positional identities on the anterior-posterior axis.
Synonyms: HOX3E; HOX3; cp19
Tractability: No criterion of Open Targets' tractability assessment is met for any kind of drug.
Gene: Protein-coding gene on chromosome 12 (54,016,931 to 54,056,030, forward strand). Ensembl gene ENSG00000198353.
Subcellular location: Nucleus
Subcellular location (Human Protein Atlas): Nucleoplasm
Pathways (Reactome):
Developmental Biology: Activation of anterior HOX genes in hindbrain development during early embryogenesis
Gene Ontology:
Molecular function: DNA-binding transcription activator activity, RNA polymerase II-specific; protein binding; RNA polymerase II cis-regulatory region sequence-specific DNA binding; sequence-specific double-stranded DNA binding; DNA-binding transcription factor activity, RNA polymerase II-specific; DNA binding; DNA-binding transcription factor activity; HMG box domain binding
Biological process: positive regulation of transcription by RNA polymerase II; anterior/posterior pattern specification; embryonic skeletal system morphogenesis; regulation of DNA-templated transcription
Cellular component: nucleoplasm; chromatin; nucleus
Genetic constraint (gnomAD): Loss-of-function variants: 15 observed, 26.77 expected, observed/expected ratio (o/e) 0.56, 90% interval 0.37 to 0.86. The upper end of that interval is the gene's LOEUF score, 0.86, which puts it in group 3 of 6, group 1 being the genes least tolerant of losing a copy. Missense variants: 342 observed, 366.05 expected, observed/expected ratio (o/e) 0.93, 90% interval 0.85 to 1.02. Synonymous variants: 165 observed, 157.57 expected, observed/expected ratio (o/e) 1.05, 90% interval 0.92 to 1.19.
Homologues: Orthologues: chimpanzee HOXC4 (100% identical), macaque HOXC4 (100% identical), pig HOXC4 (99% identical), dog HOXC4 (99% identical), guinea pig HOXC4 (99% identical), rat Hoxc4 (99% identical), mouse Hoxc4 (99% identical), rabbit HOXC4 (98% identical), tropical clawed frog hoxc4 (71% identical), zebrafish hoxc4a (70% identical). Paralogues in human: HOXD4 (51% identical), HOXB4 (50% identical), HOXA4 (49% identical), HOXA5 (36% identical), HOXB5 (35% identical), HOXC5 (31% identical), HOXB6 (30% identical), HOXA7 (30% identical), HOXB7 (30% identical), HOXC6 (28% identical), HOXA6 (28% identical), HOXD3 (28% identical), and 30 more.
Diseases named in the same sentence as HOXC4 in open-access papers:
HOXC4 is named in the same sentence as 51 diseases in open-access papers, as found by Europe PMC text mining. Sharing a sentence is not in itself a finding about the gene and the disease. The quoted sentences say what the papers report.
prostate carcinoma (6 papers, 2013 to 2022). A carcinoma that arises from epithelial cells of the prostate gland. "Recently, evidence was presented that HOXC4 can be used to detect prostate cancer at an early stage and predict recurrence, thus indicating its potential as an oncogenic promoter." (PMID 36276951, 2022). "It has been proved that aberrant expression of HOXC4 contributes to the occurrence and progression of multiple cancers, including prostate cancer, colon cancer, bladder cancer, lung cancer, etc.." (PMID 36276951, 2022). "For example, aberrant HOXC4 expression is prevalent and plays an important role in the development of prostate cancer." (PMID 34368227, 2021). "HOXC6 and HOXC4 have been previously identified as promising, easy to assay (urinary-based) biomarkers of aggressive prostate cancer that can enhance early diagnosis and predict cancer recurrence after treatment." (PMID 32012197, 2020). "Our model identified several transcription factors associated with prostate cancer metastasis, such as ETS2, HOXC4, STAT3, STAT5B, SOX4 and ZEB2." (PMID 23782521, 2013). "Aberrant expression of HOXC6 and HOXC4 is commonly detected in prostate cancer." (PMID 32012197, 2020). "To begin to address the role of HOXC4 and HOXC6 in prostate cancer, we performed RNA-seq analyses before and after siRNA-mediated knockdown of HOXC4 and/or HOXC6 and also performed ChIP-seq to identify genomic binding sites for both of these transcription factors." (PMID 32012197, 2020). "In addition, we showed colocalization of HOXC4 and HOXC6 at HOXB13 sites that are also bound by FOXA1 and AR, which have been previously linked to regulation of prostate cancer cell proliferation." (PMID 32012197, 2020). "HOXC4 overexpression of was observed in lymph node metastases of prostate cancer." (PMID 29631562, 2018). "Thus, increased levels of HOXC4 in prostate cancer may promote tumorigenesis via upregulation of YAP1." (PMID 32012197, 2020). "An unbiased analysis of DNA methylation and gene expression data using a large set of tumors from TCGA identified HOXB13, HOXC4, HOXC5, and HOXC6 in the set of the top 10 transcription factors whose expression is linked to the creation of newly active distal regulatory elements in prostate cancers." (PMID 30866492, 2019). "In summary, we have shown that HOXC4 and HOXC6 regulate critical genes affecting prostate cancer proliferation." (PMID 32012197, 2020). "Towards this goal, we identified genes that are affected by knockdown of HOXC4 and/or HOXC6 in 22Rv1 prostate cancer cells and performed ChIP-seq to characterize their genome-wide binding profiles." (PMID 32012197, 2020). "To test if this is also true for the human HOX genes that are upregulated in prostate cancer, we compared the binding sites for HOXC6 and HOXC4." (PMID 32012197, 2020). "We found that there is a striking correlation between the strength of the HOXC4 or HOXC6 binding sites and the strength of the binding sites for the key prostate cancer transcription factors HOXB13, FOXA1, and AR." (PMID 32012197, 2020). "Our studies demonstrate that HOXC4 and HOXC6 co-localize with HOXB13, FOXA1 and AR, three transcription factors previously shown to contribute to the development of prostate cancer." (PMID 32012197, 2020). "A better understanding of the molecular function of HOXC4 and HOXC6 could provide a more comprehensive understanding of prostate cancer." (PMID 32012197, 2020). "Therefore, we have developed genome-wide binding profiles for both HOXC4 and HOXC6 and identified HOXC4- and HOXC6-regulated genes in 22Rv1 prostate cancer cells." (PMID 32012197, 2020). "Thus, HOXC4 and HOXC6 are clinically relevant biomarkers of aggressive prostate cancer." (PMID 32012197, 2020). "Specifically, it is not clear if HOXC4, HOXC5, and HOXC6 are all drivers of prostate cancer or if the three proteins are all upregulated due to genomic proximity, but only one is a direct regulator of tumorigenesis." (PMID 30866492, 2019).
colorectal cancer (5 papers, 2021 to 2024). A primary or metastatic malignant neoplasm that affects the colon or rectum. "At the same time, the expressions of lnc-HOXC4-3:1, EFNA3, and LINC00520 were identified to be significantly related with the overall survival of colorectal cancer patients with P-values of 0.002, 0.008, and 0.021, respectively." (PMID 34262591, 2021).
glioma (3 papers, 2017 to 2023). A benign or malignant brain and spinal cord tumor that arises from glial cells (astrocytes, oligodendrocytes, ependymal cells). "In the present study, we found that HOXA5, HOXA7, HOXA10, HOXC4 and HOXC6 are prognostic markers in glioma patients." (PMID 28055976, 2017). "Additionally, the mIF in HPA revealed that HOXC4, HOXC5, and HOXC6 proteins were primarily expressed in nucleoplasm in the glioma cell line U-251MG." (PMID 37547473, 2023). "Importantly, we found that CD133 expression in glioma was highly correlated with the expression of HOX gene stem cell factors (HOXA5, HOXA7, HOXA10, HOXC4 and HOXC6)." (PMID 28055976, 2017).
head and neck squamous cell carcinoma (3 papers, 2021 to 2025). A squamous cell carcinoma that arises from any of the following anatomic sites: lip and oral cavity, nasal cavity, paranasal sinuses, pharynx, larynx, and salivary glands. "HOXC4 was observed to correlate closely with colon adenocarcinoma (COAD), head and neck squamous cell carcinoma (HNSC), LGG, liver hepatocellular carcinoma (LIHC), rectum adenocarcinoma (READ), and thyroid carcinoma (THCA) in terms of tumor immune cells infiltration." (PMID 41465326, 2025).
hepatocellular carcinoma (3 papers, 2021 to 2024). A malignant tumor that arises from hepatocytes. "HOXC4 regulates EMT by regulating the transforming growth factor beta (TGF-beta) signaling in HCC (Hepatocellular carcinoma)." (PMID 35254502, 2022). "Moreover, HOXC4 can promote hepatocellular carcinoma progression by transactivating Snail." (PMID 34368227, 2021). "Moreover, we found downregulation of RNF135 in hepatocellular carcinoma, downregulation of OSMR in colorectal liver metastases and upregulation of HOXC4 in cholangiocarcinoma compared to primary liver cancers and metastatic cancers." (PMID 39766812, 2024).
Obesity (3 papers, 2021 to 2025). Accumulation of substantial excess body fat. "The obesity association of the HOXC4/C5/C6 Tier-1 SNPs might be due to their linkage with rs11614913, as determined by conditional and joint analysis (COJO)." (PMID 35163195, 2022).
bladder cancer (2 papers, 2023). "The expression levels of TSHZ3, ISL, MEIS1, ZEB2, and ZFHX4 were significantly lower, whereas the expression of HOXC4 was higher in bladder cancer tissues when compared to that of normal bladder tissues." (PMID 37627900, 2023). "The expression of HOXC4, HOXC5, HOXC6, and HOXC11 was detected in 60%, 86%, 100%, and 80% of bladder cancer tissues, respectively." (PMID 37627900, 2023). "Four genes (HOXC4, HOXC5, HOXC6, and HOXC11) located at the HOX C locus as well as one gene (HOXD11) located at the HOX D locus were not expressed in normal bladder tissues but expressed in most bladder cancer tissues." (PMID 37627900, 2023).
pancreatic cancer (2 papers, 2023 to 2024). "HOXC4 is the target of miR-455-3p and its formation of miR-455-3p-HOXC4 axis may be closely related to the metastasis and prognosis of human pancreatic cancer." (PMID 36741321, 2023).
prostate tumors (2 papers, 2019 to 2020). "RNA-seq analysis reveals that, similar to our previous analysis of prostate tumors, HOXC4 and HOXC6 are robustly expressed in 22Rv1 cells." (PMID 32012197, 2020). "Using DNA methylation data from The Cancer Genome Atlas (TCGA), we have previously identified HOXC4 and HOXC6 in the set of top-ranked transcription factors (TFs) whose high expression correlates with the creation of prostate tumor-specific enhancers." (PMID 32012197, 2020). "Pathway analysis revealed that genes whose expression is positively regulated by HOXC4 and HOXC6 in prostate tumor cells are related to cancer and the cell cycle." (PMID 32012197, 2020).
acute myeloid leukemia (1 paper, 2012). Acute myeloid leukemia (AML) is a group of neoplasms arising from precursor cells committed to the myeloid cell-line differentiation. "For instance, loss of HOXA5 in breast cancer, over-expression of HOXA10 in acute myeloid leukemia (AML), gene mutations of HOXD4 in renal and colon cancer and overexpression of HOXC4 in human bladder cancer have been reported." (PMID 22768238, 2012).
alopecia (1 paper, 2009). Hair loss usually from the scalp. "The targeted disruptions of the Hoxc4,Hoxc13 and Trps1 genes were reported to cause defects in the thoracic vertebrae, alopecia, and abnormalities in the vibrissae, skull and thoracic vertebrae, respectively." (PMID 19772620, 2009).
anencephaly (1 paper, 2019). A rare neural tube defect during pregnancy, resulting in the absence of a large portion of the brain and skull in the fetus. "In conclusion, these data identify the abnormal upregulation of HOX genes, especially HOXB4, HOXC4 and HOXD1, concomitant with decreased H3K27me3 levels in human anencephaly cases." (PMID 31856916, 2019).
autoimmune disorders (1 paper, 2019). "High mRNA transcription rates for HOXC4 are associated with dysfunctions in vasculature pathways and nucleosome organization and have also been observed in autoimmune disorders." (PMID 31798633, 2019). "A lower number of methylated groups to HOXC4 would result in elevated protein levels, contributing to autoimmunity." (PMID 31798633, 2019).
brain cancer (1 paper, 2020). A primary or metastatic malignant neoplasm affecting the brain. "Notably, there were 6 HOX genes, namely HOXA2, HOXA4, HOXB2, HOXB3, HOXB4, and HOXC4, which changed expression only in brain cancer (either in GBM, brain lower grade glioma (LGG), or in both)." (PMID 32545894, 2020).
brain tumors (1 paper, 2023). "The previous research identified HOXC4 was strongly overexpressed in pediatric brain tumors, including ependymoma, medulloblastomas, glioblastoma multiforme, and juvenile pilocytic astrocytomas." (PMID 37547473, 2023).
breast carcinoma (1 paper, 2022). "For example, in breast cancer, HOXC4 expression was negatively associated with cell cycle, DNA damage, DNA repair and invasion." (PMID 36276951, 2022).
celiac disease (1 paper, 2019). An autoimmune genetic disorder with an unknown pattern of inheritance that primarily affects the digestive tract. "On the other hand, the top non-HLA DMRs in celiac disease mapped to genes related to the immune response, including NLRC5 and TMEM105 in the epithelial fraction, and CAST and HOXC4 in the immune compartment." (PMID 30718669, 2019).
COVID-19 (1 paper, 2022). A disease caused by infection with severe acute respiratory syndrome coronavirus 2. "Modulo potential confounders, a causal relation from a predisposition to take M05B to the severity of COVID-19 via HOXC4 is suggested." (PMID 36156592, 2022).
Hypertension (1 paper, 2023). The presence of chronic increased pressure in the systemic arterial system. "Multiple HOXC genes: HOXC-AS1-3, HOXC4, HOXC5, HOCX6, HOXC8, HOXC9 and HOXC10 were also shared between subsets of GORD, hypertension and precordial pain." (PMID 37410157, 2023).
keloid (1 paper, 2025). An irregularly shaped, elevated mark on the skin caused by deposits of excessive amounts of collagen during wound healing. "Notably, pivotal regulators for each sub-fibroblast cluster were discovered: IRF4 for scar, CLOCK for keloid, RUNX3 for scleroderma, and HOXC4 for normal skin." (PMID 41350567, 2025). "Additionally, we identified the pivotal regulators of each specific sub-fibroblast cluster, including IRF4 for scar-related, CLOCK for keloid-related, RUNX3 for scleroderma-related, and HOXC4 for normal skin sub-fibroblast clusters." (PMID 41350567, 2025).
medulloblastoma (1 paper, 2023). A malignant, invasive embryonal neoplasm arising from the cerebellum. "Based on the single-cell data of 13 medulloblastomas, we observed that three HOXC genes (HOXC4, HOXC5, and HOXC6) were expressed in neurons and neuroepithelial cells, specifically within the WNT and Group 3 subtypes of medulloblastoma." (PMID 37547473, 2023).
metabolic syndrome (1 paper, 2025). A cluster of metabolic risk factors for CARDIOVASCULAR DISEASES and TYPE 2 DIABETES MELLITUS. "Abnormal Hoxc4 expression in fat is sufficient to modulate metabolic function in mice and humans, while Inpp4b-KO males (but not females) have marked metabolic syndrome with higher adipose levels, insulin resistance, and inflammation in the adipose tissue." (PMID 40161793, 2025).
oral cavity cancer (1 paper, 2021). A primary or metastatic malignant neoplasm involving the oral cavity. "Furthermore, the methylation of a CpG panel including HOXC4 was predictive of survival in patients with oral cavity cancers." (PMID 34207933, 2021).
uveal melanoma (1 paper, 2020). A melanoma derived from melanocytes of the uveal tract. "In addition, it has been shown that the down-regulation function of MALAT1 restrain the development of uveal melanoma via inhibition of HOXC4." (PMID 33392203, 2020).
tumor (15 papers, 2009 to 2025). "HOXC4-associated tumor immunotherapy may yield new insights into personalized treatment and shed new light on HOXC4-associated tumorigenesis." (PMID 36276951, 2022). "A more recent review identified HOXC4 expression across 21 tumor cell lines and found that it was significantly higher than in normal tissues across 21 tumor types." (PMID 41465326, 2025). "The expression level of HOXC4 mRNA in tumor group was significantly higher than that in normal samples." (PMID 36741321, 2023). "In our study, to test the significance of HOXC4 expression in chemotherapeutic drug application, tumor cell lines with similar responses to a drug were simulated in a manner similar to that of tumor patients." (PMID 36276951, 2022). "In the following analysis, immunological correlations were systematically performed, focusing on HOXC4 expression in different tumor types in relation to TME, immune cell infiltration, MSI, and TMB." (PMID 36276951, 2022). "We hope that our research will provide novel insights into precision medicine for more individualized immunotherapy advancement in the future by elucidating the multifaceted roles HOXC4 plays in tumorigenesis and tumor immunity." (PMID 36276951, 2022). "As a result of their strongly positive correlation, it is likely that HOXC4 regulates the tumor immunosuppressive microenvironment and functions as a novel target for immunotherapy against related tumors." (PMID 36276951, 2022). "Here, our study uncovers new insights into how aberrant HOXC4 expression plays an important role in tumor immunology and as a potential biomarker for malignancy development." (PMID 36276951, 2022). "Human adipose tissue-derived MSC-EVs (AT-MSC-EVs) carrying miRNA-15a inhibit the immune escape of tumor cells by regulating the expression of homeobox C4 (HOXC4), which binds to the promoter sequence of PDL1, controlling its synthesis and membrane expression." (PMID 34830312, 2021). "As a result of the present study, HOXC4, which is increased in PC, may be a tumor promoter for the progression of this disease." (PMID 38990159, 2024). "Based on a comprehensive analysis of the expression of HOXC4 in pan-cancer, the present study found that HOXC4 was widely expressed in 31 normal tissues as well as 21 tumor cell lines, with the highest expression of HOXC4 occurring in the fallopian tube and ovary, respectively." (PMID 36276951, 2022). "To clarify the regulatory effect of miR-15a on the KDM4B/HOXC4/PD-L1 axis, we further examined the protein expression of KDM4B, HOXC4, and PD-L1 in tumor tissues using western blot." (PMID 33732698, 2021). "In our study, we show that HOXC4 and HOXC6 colocalize with HOXB13, which is present at high levels in both normal and tumor prostate tissue." (PMID 32012197, 2020). "Only HOXC4 and HOXC6 showed consistently higher expression in the tumour compared to the normal prostate, with increases of 101 and 251 fold, respectively." (PMID 24499138, 2014).